PCGF3 (polycomb group ring finger 3)
Description:
Component of a Polycomb group (PcG) multiprotein PRC1-like complex, a complex class required to maintain the transcriptionally repressive state of many genes, including Hox genes, throughout development. PcG PRC1 complex acts via chromatin remodeling and modification of histones; it mediates monoubiquitination of histone H2A 'Lys-119', rendering chromatin heritably changed in its expressibility. Within the PRC1-like complex, regulates RNF2 ubiquitin ligase activity. Plays a redundant role with PCGF5 as part of a PRC1-like complex that mediates monoubiquitination of histone H2A 'Lys-119' on the X chromosome and is required for normal silencing of one copy of the X chromosome in XX females (By similarity).
Synonyms: RNF3; RNF3A; FLJ36550; DONG1; MGC40413
Tractability: PROTAC: ubiquitination databases record sites on it.
Gene: Protein-coding gene on chromosome 4 (705,748 to 770,089, forward strand). Ensembl gene ENSG00000185619.
Subcellular location: Nucleus; Nucleus, nucleoplasm
Subcellular location (Human Protein Atlas): Nucleoplasm
Gene Ontology:
Molecular function: protein binding; histone H2AK119 ubiquitin ligase activity
Biological process: heterochromatin formation; positive regulation of DNA-templated transcription; random inactivation of X chromosome; regulation of transcription by RNA polymerase II
Cellular component: nucleoplasm; nucleus; PcG protein complex; chromatin; PRC1 complex; X chromosome
Genetic constraint (gnomAD): Loss-of-function variants: 4 observed, 18.3 expected, observed/expected ratio (o/e) 0.22, 90% interval 0.11 to 0.5. The upper end of that interval is the gene's LOEUF score, 0.5, which puts it in group 2 of 6, group 1 being the genes least tolerant of losing a copy. Missense variants: 139 observed, 209.98 expected, observed/expected ratio (o/e) 0.66, 90% interval 0.58 to 0.76. Synonymous variants: 112 observed, 89.39 expected, observed/expected ratio (o/e) 1.25, 90% interval 1.07 to 1.47.
Homologues: Orthologues: mouse Pcgf3 (98% identical), guinea pig PCGF3 (97% identical), macaque PCGF3 (96% identical), tropical clawed frog pcgf3 (93% identical), dog PCGF3 (85% identical), pig PCGF3 (82% identical), rat Pcgf3 (75% identical), chimpanzee PCGF3 (58% identical), rabbit PCGF3 (57% identical), Drosophila melanogaster l(3)73Ah (55% identical), Caenorhabditis elegans mig-32 (34% identical). Paralogues in human: PCGF5 (41% identical), PCGF1 (39% identical), PCGF2 (34% identical), PCGF6 (34% identical), BMI1 (34% identical), RNF2 (25% identical), RING1 (22% identical).
Diseases named in the same sentence as PCGF3 in open-access papers:
PCGF3 is named in the same sentence as 15 diseases in open-access papers, as found by Europe PMC text mining. Sharing a sentence is not in itself a finding about the gene and the disease. The quoted sentences say what the papers report.
lung carcinoma (3 papers, 2022 to 2024). "For example, miR-210-3p regulated the low expression of PCGF3 in lung cancer cells, and the down-regulation of PCGF3 promoted lung cancer development and metastasis." (PMID 39529637, 2024). "It was reported that PCGF3 expression in lung cancer cell lines positively regulated PI3K/AKT pathway activity." (PMID 39529637, 2024).
breast carcinoma (2 papers, 2024 to 2025). "Of the 8 candidate MD-SNP that were associated with both mammographic density and breast cancer risk in this Asian study, one (rs3806759) showed significant associations with the expression of PCGF3 in breast tissue and DGKQ in subcutaneous adipose tissue." (PMID 41272850, 2025). "BCL11A, MLLT3, ZNF521, PHC1, and PCGF3 also showed subtype-specific dysregulation in breast cancers; BCL11A, ZNF521, and PHC1 were specifically downregulated in luminal subtype cancers relative to their matched normal tissue." (PMID 39545637, 2024).
autoimmune disease (1 paper, 2024). A disorder resulting from loss of function or tissue destruction of an organ or multiple organs, arising from humoral or cellular immune responses of the individual to their own tissue constituents. "Our study provides insight into the negative regulation of ISG expression by IFN-I and suggests the potential importance of PCGF3 in the diagnosis or treatment of clinical diseases, ranging from inflammatory to autoimmune diseases." (PMID 39368978, 2024). "In addition, in vivo studies, clinical trials, and larger statistical analyses will be required to validate of PCGF3 as a prognostic biomarker for autoimmune diseases." (PMID 39368978, 2024). "Since PCGF3 down-regulates the expression of genes induced by IFN-I, we investigated the relationship between PCGF3 and ISGs in IFN-I-related autoimmune diseases." (PMID 39368978, 2024).
dermatomyositis (1 paper, 2024). Dermatomyositis (DM) is a type of idiopathic inflammatory myopathy characterized by evocative skin lesions and symmetrical proximal muscle weakness. "Additionally, we observed a negative correlation between decreased PCGF3 expression and elevated ISG expression in peripheral blood mononuclear cells (PBMCs) of patients with dermatomyositis (DM)." (PMID 39368978, 2024).
glioma (1 paper, 2022). A benign or malignant brain and spinal cord tumor that arises from glial cells (astrocytes, oligodendrocytes, ependymal cells). "As high concentration levels of α-KG serve to maintain self-renewal of embryonic stem cells, perhaps they also influence PCGF3 in IDH-wildtype glioma stem cells." (PMID 35877430, 2022).
lung adenocarcinoma (1 paper, 2024). A carcinoma that arises from the lung and is characterized by the presence of malignant glandular epithelial cells. "To determine whether PCGF3 regulates the antiviral immune response, we transfected the human lung adenocarcinoma A549 cells with small interfering RNAs (siRNAs) targeting the PCGF3 gene (si-PCGF3-1 and si-PCGF3-2)." (PMID 39368978, 2024).
non-small cell lung carcinoma (1 paper, 2022). A group of at least three distinct histological types of lung cancer, including non-small cell squamous cell carcinoma, adenocarcinoma, and large cell carcinoma. "PCGF3 was shown to promote proliferation and migration of non-small cell lung cancer (NSCLC) through the PI3K/Akt signaling pathway, while mutations in PCGF6 enhanced breast cancer cell migration and metastasis by upregulating the expression of epithelial-mesenchymal transition (EMT)-related genes." (PMID 36076977, 2022).
synovial sarcoma (1 paper, 2023). "We performed chromatin salt extraction in both HS-SY-II and SYO-I synovial sarcoma cell lines to compare the global action of PCGF1 versus PCGF3 on SS18-SSX chromatin binding." (PMID 37735617, 2023). "As expected, removing either PCGF1 or PCGF3 drastically inhibited synovial sarcoma cell proliferation." (PMID 37735617, 2023). "Hence, although PCGF3 is essential for synovial sarcoma maintenance, our results indicate that it is not required for SS18-SSX global chromatin binding, suggesting an alternative role for PRC1.3 in this context." (PMID 37735617, 2023).
tumor (8 papers, 2016 to 2025). "Moreover, Pcgf3 has previously been implicated in the regulation of tumour cell proliferation, whereas Pcgf5 and Pcgf3/5 were dispensable for embryonic stem cell self-renewal." (PMID 39933923, 2025). "Data from UALCAN online database showed that the expression level of PCGF3 was significantly higher in HCC tumor tissues than in normal tissues." (PMID 39529637, 2024). "Lastly, the expression of PCGF3 in the tumor tissues of patients with HCC, specifically HBV (+)-HCC, was significantly higher than that of paracancerous tissues." (PMID 39529637, 2024). "The high expression of PCGF3 in HCC cells and HBV-HCC tumor tissues was associated with a poorer prognosis among HCC patients." (PMID 39529637, 2024). "The list of potential tumor suppressor hits included both known factors, such as Ezh2 and Tle4, as well as novel candidates, including Kdm5c, Pcgf3, Chd1 and Pbrm1." (PMID 36631623, 2023). "Notably, the expression level of PCGF3 was significantly lower in HBeAg (+)-HCC tumor tissues than HBeAg (-)-HCC tumor." (PMID 39529637, 2024). "In our study, we identified a series of potential tumor antigens, including SREBF1, LUC7L3, LAMA5, PCGF3, HNRNPH1, KLC4, and OFD1, by systematically analyzing alternative splicing and mutation of genes in patients with HNSCC." (PMID 36467412, 2022). "The results of the present study showed that the expression of PCGF3 was significantly higher in HBeAg-negative tumor tissues compared to HBeAg-positive tissues, and among HBV-related HCC patients, there were more male patients than female patients." (PMID 39529637, 2024). "Additionally, CHD3 levels negatively correlated with tumor grade, and PCGF2 and PCGF3 levels positively correlated with ER+ status." (PMID 27863398, 2016). "Seven potential tumor antigens, [SREBF1, LUC7L3, LAMA5, PCGF3, HNRNPH1, KLC4, and OFD1], which were associated with nonsense-mediated mRNA decay factor expression, overall survival, and infiltration of APCs and would thus induce a potent anti-tumor T-cell response." (PMID 39399167, 2024).
cancer (5 papers, 2021 to 2025). A tumor composed of atypical neoplastic, often pleomorphic cells that invade other tissues. "Thus, we hypothesized that IFN-exo or miR-106b-3p regulated the malignant biological functions of cancer cells by reducing the PCGF3 expression and inhibiting PI3K/AKT signaling pathway activity in HBV (+)-HCC." (PMID 39529637, 2024). "In addition, the PCGF3 gene, which is a member of the polycombgroup of proteins, has been shown to be involved in deregulating proteins that could lead to cancer cell transformation." (PMID 36467412, 2022). "Recent studies have revealed that the PCGF family of proteins (PCGF1 (Nspc1), PCGF2 (Mel-18), PCGF3, PCGF4 (Bmi1), PCGF5 and PCGF6 is robustly elevated in diverse human cancers and promotes cancer progression." (PMID 34148069, 2021). "Given the inconsistencies regarding the expression of PCGF3 in cancer and the lack of reports on PCGF3 in HBV-related HCC, the present study analyzed the data of HCC patients in the UALCAN online database." (PMID 39529637, 2024).
infection (3 papers, 2011 to 2024). The state of being infected such as from the introduction of a foreign agent such as serum, vaccine, antigenic substance or organism. "Consistently, knockdown of PCGF3 increased the expression levels of ISGs (ISG15, IFIT1, OAS2, MX1 and IRF7) and IFNB1, and decreased the VSV replicates (RNA level and virus titer) after VSV infection." (PMID 39368978, 2024).
PCGF3 also shares sentences with these, for which no sentence is quoted: central precocious puberty (1 paper); mesothelioma (1); pituitary adenomas (1); Prader-Willi syndrome (1).